CNGA3 (cyclic nucleotide gated channel subunit alpha 3)
Diseases named in the same sentence as CNGA3 in open-access papers (continued):
Sharing a sentence is not in itself a finding about the gene and the disease.
achromatopsia (continued). "Potential phenocopies of the optical gap appearance on OCT imaging include achromatopsia (associated with CNGA3 or CNGB3 mutations), cone dystrophy (associated with GUCY2D or other genes), RP1L1-associated occult macular dystrophy, and acquired diseases such as solar retinopathy." (PMID 38066771, 2023). "Previously, fundus examination and OCT findings of CNGA3 variants revealed age-dependent foveal hyperfluorescence patterns in achromatopsia affected young patients in comparison to older patients who have foveal atrophy and outer retinal cavitation along with unique hypo/hyperfluorescence." (PMID 35456423, 2022). "Of 19 diseases, 10 had >10 participants: ABCA4 retinopathy; CNGB3- and CNGA3-associated achromatopsia; RPGR-associated disease; RPE65-associated disease; blue cone monochromacy (BCM); Bornholm eye disease (BED); TYR- and OCA2-associated oculocutaneous albinism; and GPR143-associated ocular albinism." (PMID 35704304, 2022). "Recently promising results from a PhaseI/II trial for CNGA3-associated achromatopsia were published showing that the AAV vector was well-tolerated and initial measures of efficacy were promising, including improvement in visual acuity, contrast sensitivity, and cone function [NCT02610582]." (PMID 33815052, 2021). "In particular, our data may imply that in future clinical trials, restoration of 20% functional CNGA3 protein may form functional CNG channels and rescue the cone response in CNGA3-associated achromatopsia." (PMID 34360834, 2021). "Our data also possess implications for future CNGA3-associated achromatopsia clinical trials, whereby restoration of only 20% functional CNGA3 protein may be sufficient to form functional CNG channels and thus rescue cone response." (PMID 34360834, 2021). "However, constitutive synthesis of cGMP at the inner segment compartment of cones has been shown to be very toxic and the basis of the physiopathology in mouse models of achromatopsia caused by null mutations in cone CNG-channel subunits CNGA3 and CNGB3." (PMID 31980596, 2020). "Similarly, to understand the CNGA3-associated achromatopsia, CRISPR elements were microinjected in zebrafish embryo to target cnga3a and cnga3b and disrupt the gene functions leading to impaired visual functions." (PMID 32967234, 2020). "Interestingly, mutations in CNGA3 have been linked to total colour blindness, also referred to as rod monochromacy (RM) or complete achromatopsia, a rare, autosomal recessive inherited and congenital disorder." (PMID 32424050, 2020). "In humans, CNGA3 is implicated in total color blindness (achromatopsia)." (PMID 30415424, 2018). "Mutations associated with the CNGB3 subunit are most common in European subjects (ACHM3; OMIM# 262300) and account for 50% of all known cases worldwide, whereas the CNGA3-associated achromatopsia (ACHM2; OMIM# 216900) accounts for ~30% of all diagnosed cases thus far." (PMID 26407004, 2015). "We have identified pathogenic mutations in CNGA3 in two independent UAE achromatopsia families." (PMID 18636117, 2008). "CNGA3 mutations are expected to account for about 20%–30% of achromatopsia cases." (PMID 18636117, 2008). "Genetic variants of both CNGA3 or CNGB3 have been reported in humans with achromatopsia (ACHM), cone–rod dystrophy or other disorders such as progressive cone dystrophy." (PMID 35456423, 2022). "Thus, it can be concluded that mutating the Cnga3 locus to disrupt the functional tetrameric CNG channels may ultimately require more potent STOP cassettes to generate a reversible achromatopsia mouse model." (PMID 34360834, 2021). "Their phenotype, characterized by photophobia, congenital nystagmus, and moderate visual impairment, was consistent with CNGA3-related achromatopsia.HOPE analysis showed that the wild-type residue proline is located in the cyclic nucleotide-binding domain." (PMID 40141357, 2025).
achromatopsia (continued). "The CNGA3 genotype correlating closely with the phenotype of achromatopsia in Family 1 also provides additional evidence for an association between this variant and the presence of clinical symptoms." (PMID 40737315, 2025). "Up to 70% of achromatopsia patients carry pathogenic mutations in CNGB3, while another 25% of patient cases have pathogenic CNGA3 variants." (PMID 40448196, 2025). "Clinical studies of CNGA3 gene supplementation have been conducted with promising results for achromatopsia." (PMID 40448196, 2025). "SR injection of rAAV2 carrying the CNGA3 gene successfully restored sheep’s photopic vision with a long-lasting effect, contributing to approval of clinical trials in CNGA3 achromatopsia patients (NCT02935517, NCT02610582, NCT03278873)." (PMID 39472677, 2024). "As a large animal model for human CNGA3 achromatopsia, Awassi sheep have been used, since they were described as demonstrating congenital day blindness, an autosomal recessive hereditary disease." (PMID 39273686, 2024). "Pathogenic variants in different genes such as CNGA3, CNGB3, GNAT2, PDE6H, ATF6 and PDE6C have been reported to be relevant to COD, cone-rod dystrophy (CORD) and achromatopsia (ACHM) diseases." (PMID 38956522, 2024). "Preliminary safety and efficacy of AGTC-401 and AGTC-402 in CNGB3- and CNGA3-related achromatopsia were presented at ARVO." (PMID 39273686, 2024). "There are over 100 and 40 mutations identified in CNGA3 and CNGB3, respectively, accounting for 70–80% of the total achromatopsia cases." (PMID 37446378, 2023). "Mutations in CNGA3 and CNGB3 are associated with achromatopsia, progressive CRD, and early-onset macular degeneration." (PMID 37446378, 2023). "During primary cone degeneration, caspase-3 activation was found in the Cnga3−/− mouse model, a widely used model of achromatopsia, a type of primary cone degeneration IRD." (PMID 35054919, 2022). "This can be seen also for instance in subjects with CNGA3-achromatopsia, in whom a hyperactivity in the rod system has been shown by full-field pupillography." (PMID 35262734, 2022). "Achromatopsia is a cone-dystrophy commonly studied, with many studies investigating the Cnga3−/−, Cngb3−/− models which make up approximately 30% and 50% of achromatopsia cases, respectively, as well as the cone photoreceptor function loss 1 (Cpfl) model." (PMID 35054919, 2022). "This in vitro model was designed to assess vectors with a transgene cassette expressing the CNGA3 subunit of the human cone-specific CNG channel, which would be used to treat achromatopsia patients with mutations in this gene." (PMID 35562929, 2022). "As proof‐of‐concept, intravitreal Cnga3 delivery using AAV2.GL lead to cone‐specific expression of Cnga3 protein and rescued photopic cone responses in the Cnga3−/− mouse model of achromatopsia." (PMID 33616280, 2021). "To evaluate the efficiency of the newly engineered capsids in a relevant preclinical disease model, we performed a proof‐of‐concept gene supplementation study in the Cnga3−/− mouse model of achromatopsia using the cone‐favouring AAV2.GL capsid." (PMID 33616280, 2021). "Using the Cnga3−/− mouse model of achromatopsia, we also report a first validation of AAV2.GL in a proof‐of‐concept study for restoring cone photoreceptor function after intravitreal gene supplementation therapy." (PMID 33616280, 2021). "Current studies include Phase 1/2 trials in CNGA3- and CNGB3-associated achromatopsia (Sponsors: AGTC; MeiraGTx; STZ eyetrial)." (PMID 34768969, 2021). "CNGA3 and CNGB3 mutations are the two most common causes and are responsible for approximately 80% of all achromatopsia cases." (PMID 34360834, 2021). "Recently, phase I/II retinal gene therapy trials for CNGA3-mediated achromatopsia demonstrated some level of cone photoreceptor function restoration in adult patients." (PMID 34360834, 2021).
achromatopsia (continued). "Pathogenic variants in six genes (CNGA3, CNGB3, GNAT2, ATF6, PDE6C, and PDE6H) have been identified in humans with achromatopsia (OMIM 216900)." (PMID 34830323, 2021). "There are several gene therapies reported in achromatopsia animal models: sheep, and mouse models with CNGA3-related achromatopsia, mouse and canine models with CNGB3 mutations, and a mouse model with a genetic defect in the GNAT2 gene." (PMID 32953936, 2020). "The case of proband 56‐1 highlights a dilemma for future therapeutic intervention especially in view of the current achromatopsia CNGA3 gene therapy trials [NCT 02610582, 03278873, 03758404, and 02935517]." (PMID 32783370, 2020). "Mutations in the cone photoreceptor CNG channel subunits CNGA3 and CNGB3 are associated with achromatopsia and cone dystrophies." (PMID 31182474, 2019). "As a result of these successes in various animal models, phase I/II human clinical trials are in progress for CNGB3 (NCT02599922) and CNGA3 (NCT02610582) achromatopsia using AAV-mediated delivery of these genes." (PMID 30667376, 2019). "Mutations in genes encoding the channel subunits CNGA3 and CNGB3 account for ∼80% of all cases of achromatopsia and are associated with progressive cone dystrophies." (PMID 31182474, 2019). "The results of a large-animal model provide an important data base for gene therapy in CNGA3-achromatopsia patients." (PMID 29131863, 2017). "Although a greater variety of specific mutations in CNGA3 have been linked to achromatopsia compared to mutations in CNGB3, mutations in CNGA3 only account for 20–30% of the known cases." (PMID 26106334, 2015). "Mutations in CNGA3 and CNGB3, which encode similar subunits in cone photoreceptor channels, are a major cause of achromatopsia." (PMID 25650393, 2015). "Mutations in the two subunits (CNGA3, CNGB3) of cone photoreceptor cyclic nucleotide-gated (CNG) channels account for approximately 75% of all cases of complete achromatopsia." (PMID 22509403, 2012). "Mutations in the alpha subunits of the cone cyclic nucleotide-gated channels (CNGA3) are responsible for about 1/4 of achromatopsia in the U.S. and Europe." (PMID 22509403, 2012). "This would have important implications for human Cnga3 achromatopsia which is characterized by a gradual and variable degree of cone loss." (PMID 22509403, 2012). "The results provide the foundation for development of an AAV5-based gene therapy trial for human CNGA3 achromatopsia." (PMID 22509403, 2012). "In summary, we demonstrate restoration of cone function for at least 5 months in a naturally occurring mouse model of Cnga3 achromatopsia using an AAV5 vector." (PMID 22509403, 2012). "This study is the first demonstration of substantial, relatively long-term restoration of cone-mediated light responsiveness and visual behavior in a naturally occurring mouse model of CNGA3 achromatopsia." (PMID 22509403, 2012). "Mutations in CNGA3, CNGB3, and GNAT2 have been associated with the majority of studied cases of achromatopsia." (PMID 18636117, 2008). "Results from 3 of the trials have been formally published in peer‐reviewed journals: these have related to therapies for CNGA3‐associated achromatopsia (with 3‐year results published), CNGB3‐associated achromatopsia (6 month results published) and GUCY2D‐associated LCA." (PMID 40013354, 2025). "Notably, CNGA3 and CNGB3 function together by forming a heterotetramer cyclic nucleotide-gated (CNG) channel resulting in up to 95% of achromatopsia patients carrying pathogenic defects in the CNGA3/CNGB3 channel complex (cone CNG channel)." (PMID 40448196, 2025). "We established a three-dimensional protein structure-based proteoform analysis of the CNGA3/CNGB3 complex to better understand CNG channel-dependent achromatopsia pathology and determined the pathogenicity and potential disease pathology of our patient’s mutation." (PMID 40448196, 2025).
achromatopsia (continued). "Myopia is a prominent feature of some of the disorders, including blue cone monochromacy, Bornholm eye disease, PDE6‐associated achromatopsia (but not achromatopsia associated with CNGA3 or CNGB3) and ARR3‐associated disease (in females)." (PMID 40013354, 2025). "Mutations in the genes encoding the cone CNG channel (CNGA3 and CNGB3) lead to achromatopsia." (PMID 36830806, 2023). "Importantly, a mutation that leads to a R-to-W substitution of the corresponding human CNGA3 sequence (p.R410W) was also found in achromatopsia patients." (PMID 36830806, 2023). "However, several trials target the CNGA3 and CNGB3 gene mutations in another IRD, achromatopsia (ACHM) (NCT03278873, NCT02610582)." (PMID 37763275, 2023). "Here, we described the molecular findings and clinical manifestations of achromatopsia, a partial or total absence of color vision, co-segregating with three known missense variants of CNGA3 in three large consanguineous Pakistani families." (PMID 35456423, 2022). "In summary, although CNGA3—together with CNGB3—contributes the major parts of the CNG protein channel, where many achromatopsia patients carry mutations in both genes, merely having a small amount of normal CNGA3 protein is sufficient to form “functional” CNG channels." (PMID 34360834, 2021). "Future studies may want to explore more powerful STOP cassettes in order to target the Cnga3 gene and create a reversible mouse model of achromatopsia that more accurately recapitulates the human phenotype." (PMID 34360834, 2021). "In sheep, a form of CNGA3-related achromatopsia has been characterized (OMIA 001481-9940)." (PMID 34830323, 2021). "In addition to eGFP reporter‐based studies, we assessed the efficacy of AAV2.GL in a preclinical proof‐of‐concept study for intravitreal gene supplementation in degenerating cones of the Cnga3−/− mouse model of achromatopsia." (PMID 33616280, 2021). "Here, we attempted two rounds of gene augmentation to generate recoverable mouse models of achromatopsia including a Cnga3 model with a knock-in stop cassette in intron 5 using Easi-CRISPR (Efficient additions with ssDNA inserts-CRISPR) and targeted embryonic stem (ES) cells." (PMID 34360834, 2021). "Therefore, we chose the Cnga3 gene as our target to generate our potentially reversible achromatopsia mouse model." (PMID 34360834, 2021). "Day blind CNGA3 mutant Improved Awassi sheep provide a large animal model for achromatopsia." (PMID 33168939, 2020). "Here, we explored the disease mechanisms in the Cnga3 knockout (KO) mouse model of achromatopsia." (PMID 33374621, 2020). "Here, we explored cone cell death mechanisms in the Cnga3 KO mouse model of achromatopsia." (PMID 33374621, 2020). "In this case, the retinal appearance was in keeping with CNGA3‐related achromatopsia, however, an ERG is required to determine whether there are diminished or absent photopic responses, with normal scotopic responses, compared with those seen for RP." (PMID 32783370, 2020). "Here, long-term Validation of capsid mutants AAV8 vector for CNGA3-achromatopsia has been demonstrated in a mouse model, but AAV vector performance in human patients could be different from mice." (PMID 29131863, 2017). "Treatment for achromatopsia was successful in CNGA3-KO and CNGB3-KO mice." (PMID 25650393, 2015). "In other forms of inherited retinal degeneration such as achromatopsia, progressive cone dystrophy, and AMD previously linked to the R563H and Q655X mutations of the cyclic nucleotide gated channel alpha 3 (CNGA3) subunits, activation of the UPR has also been demonstrated." (PMID 24068865, 2013). "Population-wide screening for CNGA3 mutations, in addition to genetic counseling in UAE families and subpopulations affected by achromatopsia, could be undertaken to determine carrier status and to provide informed risk for individual families." (PMID 18636117, 2008).
achromatopsia (continued). "Our approach is specifically tailored to compliment clinical genomics in determining pathogenicity in CNGA3-associated achromatopsia, but future perspectives include extrapolation to non-Mendelian disorders with coding variants and prominent effects on a functional protein level." (PMID 40448196, 2025). "As clinical trials evaluating the safety and efficacy of rAAV-based gene augmentation therapy in CNGA3 achromatopsia patients are ongoing, the study presented here may have implications for these trials as well as for other ocular gene augmentation therapy trials utilizing rAAV." (PMID 39472677, 2024). "Moreover, gene therapy of achromatopsia caused by mutations in the CNGA3 gene has already reached the clinical phase, and a trial with subretinal AAV8.CNGA3 gene therapy in nine patients with CNGA3-linked achromatopsia demonstrated a good safety profile over 3 years." (PMID 37079081, 2023). "Four of the CNG channel genes are linked to inherited retinal disorders (IRD): mutations in CNGA1 and CNGB1 are known to cause retinitis pigmentosa (RP) and mutations in CNGA3 and CNGB3 cause achromatopsia (ACHM)." (PMID 36830806, 2023). "The similar clinical presentation between familial achromatopsia in humans and bovine recessive day-blindness led to the hypothesis that a protein-changing variant within CNGA3, CNGB3, GNAT2, ATF6, PDE6C, and PDE6H would be associated with achromatopsia of Original Braunvieh calves." (PMID 34830323, 2021). "Biallelic mutations in CNGA3 and CNGB3 genes are the most common cause of congenital autosomal recessive achromatopsia (ACHM), which affects 1 in 30,000 individuals." (PMID 32967234, 2020). "These experiments show the Tri-Asp motif is necessary for proper cone CNG channel formation, but raises the question why mutations in CNGB3 result in the loss of cone function and achromatopsia when CNGA3 can form a functioning homomeric channel in the absence of CNGB3." (PMID 32260251, 2020). "Genetic defects in CNGA3 and CNGB3, encoding two structurally related subunits of cone CNG channels, lead to achromatopsia (ACHM)." (PMID 26407004, 2015). "For example, ongoing clinical trials are targeting the cyclic nucleotide-gated cation channel alpha-3 (CNGA3) and beta-3 (CNGB3) genes responsible for achromatopsia, with early results indicating safety and potential efficacy." (PMID 40357281, 2025). "The CNGA3 and CNGB3 genes contribute to approximately 65-80% of achromatopsia cases, and therefore, research has been focused on the Cnga3−/− and Cngb3−/− animal models to study primary cone degeneration." (PMID 35054919, 2022). "Mouse models of CNGA3 and CNGB3 achromatopsia showed cone dysfunction and have been used to evaluate the efficacy of gene augmentation therapy." (PMID 25650393, 2015). "Mutations in CNGA3 and CNGB3 cause achromatopsia but do not show a consistent association with myopia." (PMID 40535564, 2025). "In CNGA3-achromatopsia patients, a proportion of patients with a normal foveal ellipsoid zone on the OCT was significantly higher than that of patients with other causative genes (62.5% vs. 16.7%; p = 0.023)." (PMID 36833446, 2023). "To generate a novel, reversible mouse model of achromatopsia, we used Easi-CRISPR (Efficient additions with ssDNA inserts-CRISPR) technology to knock-in floxed-miniSTOP cassettes (393 bps) in intron 5 of the Cnga3 gene." (PMID 34360834, 2021). "Mutations in CNGA3 (MIM#600053), CNGB3 (MIM#605080), GNAT2 (MIM#139340), and PDE6C (MIM#600827) have been detected in four probands with OT, which all encode cone phototransduction pathway proteins, suggesting a pathomechanistic overlap with achromatopsia (ACHM)." (PMID 28829391, 2017). "The low proportion of patients with FAF Groups 3 and 4, and OCT Grades 3 and 4 in our study, can support the speculation that those stages are short transitional state of the disease natural history, in contrast to CNGB3-, CNGA3-, and PDE6C-achromatopsia where Grade 4 is more common." (PMID 33737031, 2021).